DNMT1 (DNA methyltransferase 1)
Diseases named in the same sentence as DNMT1 in open-access papers (continued):
Sharing a sentence is not in itself a finding about the gene and the disease.
depression (14 papers, 2020 to 2025). "Epigenetic repression of GAD67 via DNMT1 in the central amygdala similarly drives pain-related depression, pointing to gene–environment interactions that erode inhibitory tone." (PMID 41373485, 2025). "In another study, it was demonstrated that miR-152(-3p) regulated chronic-pain-induced depression-like behaviors by targeting DNA methyltransferase 1 (DNMT1)." (PMID 39273498, 2024). "The results in postmortem patients with depression also showed that the expression levels of DNMT1 mRNA in the prefrontal lobe and amygdala were decreased, which was the same as that in the peripheral blood." (PMID 33101076, 2020). "It was found that the expression levels of Dnmt1 were significantly increased in the hippocampus of depression-like rats, and decreased after antidepressant treatment with escitalopram." (PMID 33101076, 2020). "In the depression animal model established by maternal deprivation and social isolation, Dnmt1 expression and Nr3c1 promoter methylation level of female rats were higher than those in male rats." (PMID 33101076, 2020). "Notably among the hub genes identified, DNMT1, RRM2B and GCA have previously been shown to be associated with suicide or depression." (PMID 37398042, 2023). "However, Dnmt1 knockout (KO) mice displayed an anxiolytic and anti-depression phenotype, while Dnmt3a deficiency does not alter behavior, which indicated Dnmt1 and Dnmt3a played distinct roles in controlling emotion in mice." (PMID 33171840, 2020). "Chronic stress has been shown to increase DNMT1 and DNMT3a levels in the nucleus accumbens and treatment with DNMT inhibitors reversed depression-like behaviors." (PMID 34276306, 2021). "Although the hypothalamus is related to some aspects of depression and dopaminergic projections from the ventral tegmental area to the nucleus accumbens pass through the hypothalamus, no changes in the DNMT1 and HCN1 gene expression have been revealed." (PMID 36766503, 2023). "This study aimed to investigate whether the maternal methyl-enriched diet (MED), which affects DNA methylation, can alter DNMT1, HCN1, and TH gene expression and modify absence seizures and comorbid depression in WAG/Rij offspring." (PMID 36766503, 2023). "Therefore, our results demonstrated that DNMT1 and DNMT3a regulate the level of DNA methylation in the CRMP2 gene promoter region, thus affecting the expression of CRMP2 in the hippocampus of rats and participating in the pathogenesis of depression." (PMID 33815064, 2021).
esophageal cancer (14 papers, 2014 to 2025). A primary or metastatic malignant neoplasm involving the esophagus. "The researchers found an inverse association between esophageal cancer and the G allele of the DNMT1 rs2228612 polymorphism." (PMID 39597087, 2024). "We also found an inverse association between the variant G allele of DNMT1 rs2228612 and esophageal cancer." (PMID 25337902, 2014). "There was an inverse association between DNMT1 rs2228612 and esophageal cancer (any G versus A/A, SBOR: 0.60, 95% posterior limits: 0.39, 0.94)." (PMID 25337902, 2014). "For DNMT1 polymorphism, rs2228612 was inversely associated with esophageal cancer in the dominant genetic model (any G versus A/A, SBOR: 0.60, 95% posterior limits: 0.39, 0.94)." (PMID 25337902, 2014). "This suggests that miR‐148a‐3p potentially governs cell proliferation and invasion in oesophageal cancer by selectively targeting DNMT1." (PMID 40387409, 2025). "In conclusion, the high expression of DNMT1 in esophageal cancer compared with normal tissue probably reflects the increased methylation of RASSF1A gene promoter CpG island." (PMID 25886188, 2015). "Similarly, it has been reported that lncRNA ADAMTS9-AS2 can recruit DNMT1/3, inhibiting the proliferation and migration of esophageal cancer cells." (PMID 38965467, 2024). "In this study, we investigated the role of DNMT1 in esophageal cancer stem cells." (PMID 29721170, 2018). "With the comprehensive results above, we could presume that DNMT1 high expression in esophageal cancer tissues could lead to high methylation in RASSF1A gene promoter CpG island." (PMID 25886188, 2015). "DNMT1 expression abnormalities may be involved in the process of esophageal cancer, but the development in the majority of esophageal cancers is related to multiple factors, genes, and multiple-step processes." (PMID 25886188, 2015). "Notably, 2i treatment also markedly down-regulated the levels of UHRF1 and DNMT1 proteins in all esophageal cancer cells (KYSE150, KYSE410, KYSE140, KYSE520, KYSE30, and KYSE450) with the only one exception of KYSE510, in which UHRF1 protein level was unchanged." (PMID 30696879, 2019). "FDX1 expression correlated negatively with that of TET2 and DNMT1 in BRCA, esophageal carcinoma (ESCA), GBM, HNSC, LIHC, LUAD, LUSC, and PCPG and correlated positively in skin cutaneous melanoma (SKCM)." (PMID 36210836, 2022). "miR‐148a‐3p directly targets DNMT1, and a negative correlation exists between the expression levels of miR‐148a‐3p and DNMT1 in the context of oesophageal cancer." (PMID 40387409, 2025). "For instance, silencing the expression of LINC00184 in esophageal cancer inhibited cell proliferation, migration, invasion, and glycolysis and restored the ability of mitochondrial oxidative phosphorylation by up-regulating the expression of PTEN mediated by DNMT1 (DNA methyltransferase 1)." (PMID 36124026, 2022). "We found that for 7 esophageal cancer cell lines PD0325901 treatment down-regulated both UHRF1 and DNMT1 at the level of proteins and mRNAs in all lines except KYSE510, a result that is essentially identical to that of 2i on UHRF1 and DNMT1 proteins and mRNAs in these cells." (PMID 30696879, 2019). "The functions of DNMT1 in the regulation of esophageal cancer stem cells have not been studied." (PMID 29721170, 2018).
T-cell lymphomas (14 papers, 2007 to 2025). "Conversely, loss of DNMT1 has been shown to delay the onset of T-cell lymphoma by suppressing tumor cell proliferation." (PMID 29100357, 2017). "It was shown that reduction in Dnmt1 expression in mice carrying a hypomorphic Dnmt1 allele induced DNA hypomethylation within centromeric or pericentric regions, genome instability, and development of T cell lymphomas." (PMID 28587163, 2017). "Global hypomethylation in mice results in chromosome duplications and invasive T-cell lymphomas at four months of age, and in mouse ES cells, loss of Dnmt1 also causes global hypomethylation and increased mutation rates." (PMID 26808831, 2016). "Reductions in DNMT1 are also associated with pathological conditions such as aggressive T-cell lymphoma." (PMID 24586322, 2014). "Thus, the authors suggested that DNMT1 was implicated in the maintenance of the tumor phenotype in MYC-induced T-cell lymphomas and in the de novo methylation during tumorigenesis." (PMID 35326620, 2022). "In mice with only 10% expression of DNA methyltransferase 1 (Dnmt1), genome-wide hypomethylation resulted in a high incidence of chromosome 15 trisomy, leading to aggressive T cell lymphoma." (PMID 34272358, 2021). "In this study, we abrogated tumorigenesis in an NPM-ALK–driven T-cell lymphoma model by conditionally targeting the DNA methyltransferase Dnmt1 by Cd4-Cre induced deletion." (PMID 33310759, 2021). "Remarkably, it has been demonstrated that 80% of mice with a knockdown of DNMT1, which results in a hypomethylated genome, develop mature T-cell lymphomas." (PMID 30701021, 2018). "Studies have shown that DNMT1 deletion leads to DNA demethylation and that DNMT1 is critical for T-cell lymphoma prevention and maintenance, contributing to aberrant methylation by de novo and maintenance methylation." (PMID 28127428, 2017). "Dnmt1 hypomorphic mice exhibit increased chromosomal duplications and rearrangements, and develop invasive T-cell lymphomas at approximately four months of age." (PMID 26808831, 2016). "Mice with functional disruption of DNA methyltransferase 1 (DNMT1) function demonstrate significant genomic hypomethylation in all tissues and develop aggressive T-cell lymphomas with chromosomal instability." (PMID 19305507, 2009). "Notably, deletion of Dnmt1 in an MYC-driven T-cell lymphoma model delayed lymphomagenesis and resulted in reduced proliferation of tumor cells." (PMID 33310759, 2021).
narcolepsy (13 papers, 2014 to 2025). A sleep disorder characterized by a tendency for excessive sleepiness during the day which occurs even after adequate sleep in the nighttime. "After detection of the causal DNMT1 mutation, we revaluated our patient and elicited symptoms suggestive of narcolepsy, which was then confirmed in a polysomnographic examination." (PMID 35172867, 2022). "Ten years ago, heterozygous mutations in the DNMT1 gene were described for the first time in the setting of variable neurological phenotypes encompassing sensory neuropathy, cerebellar ataxia, deafness, narcolepsy and cognitive disturbances." (PMID 35172867, 2022). "Further, causal mutations in the replication foci targeting sequence domain of DNA methyltransferase 1 (DNMT1) were found in families with atypical narcolepsy and patients showed the genome-wide methylation abnormality." (PMID 37380713, 2023).
heart failure (12 papers, 2016 to 2025). Inability of the heart to pump blood at an adequate rate to meet tissue metabolic requirements. "In doxorubicin-induced heart failure models, DNMT1 was found to be upregulated, promoting methylation of miR-152-3p promoter and consequently decreasing its expression." (PMID 41226851, 2025). "DNA methyltransferase 1 (DNMT1) plays a harmful role in heart failure by inhibiting mitophagy through the miR-152-3p/ETS1/RhoH signaling axis." (PMID 41226851, 2025). "In contrast, another study showed that high expression of DNMT1 suppresses miR152–3p, causing downregulation of ETS1 and RhoH, decreasing mitophagy and autophagy, and aggravating heart failure." (PMID 38427976, 2024). "One study outlined the role of DNA methyltransferase 1 (Dnmt1) in murine HF models; this study showed that Dnmt1 is upregulated in rat heart failure and cardiac injury models, correlating with an upregulation of DNMT1 in samples from HCM patients." (PMID 34445422, 2021). "Recently, DNMT1 is found to be up‐regulated in the atrium of rats with isoproterenol‐induced heart failure." (PMID 34235895, 2021). "Depletion of DNMT1 in a rat model of heart failure significantly improved cardiac functions." (PMID 38427976, 2024). "Histone deacetylase 3 increases the level of DNMT1 by deacetylating the DNMT1 ubiquitination pathway, which in turn inhibits the expression of SHP‐1, thereby promoting heart failure." (PMID 40497340, 2025). "HDAC3 deacetylates DNA methyltransferase 1 (DNMT1) to inhibit ubiquitination-mediated degradation, which promotes the expression of DNMT1, which inhibits the expression of SHP-1 by methylation of the promoter region, thereby leading to heart failure induced by cardiomyocyte hypertrophy." (PMID 40710369, 2025).
periodontitis (12 papers, 2014 to 2025). An acute or chronic inflammatory process that affects the tissues that surround and support the teeth. "This suggests that the A allele may be “protective” against periodontitis, although the specific mechanism by which the genotype affects DNMT1 function remains unclear." (PMID 40599550, 2025). "Similar transcript levels of DNMT1 and DNMT3a are expressed in gingival biopsies from periodontitis patients and healthy controls." (PMID 33256844, 2020). "Martins and co-workers [17•] reported on a down-regulation of DNMT1 and an up-regulation of acetylated histone 3 in the epithelial cells close to the inflammatory lesion in a mice periodontitis model." (PMID 29201597, 2017). "Both in vitro and in vivo experimental models have demonstrated that Porphyromonas gingivalis can influence DNMT1 expression and that DNMT1 may exert protective effects against periodontitis." (PMID 40599550, 2025). "Notwithstanding these findings, comprehensive mechanistic investigations are warranted to delineate the precise involvement of DNMT1 in the pathogenesis of periodontitis and to characterize the functional implications of the rs2288349 polymorphism on its regulatory mechanisms." (PMID 40599550, 2025). "One of the main findings of the present study was the large difference in DNA methylation levels in periodontitis lesions between current smokers and non‐smokers, as revealed by the significantly lower density of DNMT1‐positive cells in current smokers than in non‐smokers." (PMID 35766184, 2022). "Compared to control samples, the methyltransferases DNMT1, DNMT2 and DNMT3B were significantly downregulated in periodontitis samples, while significantly higher DNMT3A expression was observed in periodontitis samples." (PMID 40267082, 2025). "Gene correlation analysis demonstrated that EZH2 gene was highly positively correlated with DNMT1 and DNMT3N in periodontitis samples (FDR<0.01)." (PMID 34347624, 2021). "A significant up-regulation of DNMT1 and TET1 mRNA was found in periodontitis patients compared to healthy controls." (PMID 29201597, 2017). "In gingival fibroblasts, DNMTs are also regulated by inflammatory mediators that play a central role in periodontitis pathogenesis: IL-1β upregulates DNMT1 and downregulates DNMT3a expression, whereas exposure to PGE2 leads to downregulation of both DNMT1 and DNMT3a." (PMID 33256844, 2020). "We have detected a significant upregulation in the mRNA levels of enzymes that modify chromatin, DNMT1 and TET1, in the periodontitis tissue samples (data not shown)." (PMID 25147584, 2014).
type 2 diabetes (12 papers, 2013 to 2023). "Such cells have however been detected in pathological situations like type 1 and type 2 diabetes and in mice following loss of Arx and Dnmt1." (PMID 34385420, 2021). "mir-433 (fold change of −9,6) is activated by the estrogen receptor ESRRG, in which several SNPs have been associated with higher risk of type 2 diabetes by GWAS and that acts as a co-activator of the demethylating enzyme Dnmt1." (PMID 23335998, 2013). "Our previous genome-wide association studies showed that DNA methyltransferase 1 (DNMT1) is associated with increased susceptibility to type 2 diabetes (T2D) in Han Chinese individuals." (PMID 27322146, 2016). "Here, the authors show that in Type 2 diabetic mouse models, Dnmt1 is upregulated in hematopoietic stem cells, leading to impaired differentiation towards macrophages, reduced macrophage infiltration in the wound and skewed M1/M2 polarization." (PMID 29295997, 2018). "By using another obese and type 2 diabetic model, the BTBR ob/ob mice, this study showed a decrease in Dnmt1 gene expression due to the metabolic condition, both in males and females." (PMID 37091852, 2023). "An approved drug for the treatment of type 2 diabetes (glyburide) and an approved anticancer drug known as HDAC inhibitor (panobinostat) were among the active compounds with DNMT1." (PMID 33375520, 2020). "For example, individuals with type 2 diabetes had higher DNMT3B levels in cultured myotubes and decreased TET1 expression in adipose tissue vs tissue from individuals without type 2 diabetes, while palmitate exposure decreased DNMT3A and DNMT1 expression in human pancreatic islets." (PMID 35307762, 2022).
autoimmune disease (11 papers, 2015 to 2025). A disorder resulting from loss of function or tissue destruction of an organ or multiple organs, arising from humoral or cellular immune responses of the individual to their own tissue constituents. "Aberrant hypermethylation of the Foxp3-TSDR, often driven by dysregulated DNA methyltransferases like DNMT1, disrupts Treg differentiation and function, contributing to the pathogenic Th17/Treg imbalance observed in autoimmune diseases, including SLE." (PMID 40918088, 2025). "The study identified miR-21 and miR-148a as key contributors to the reduction in DNA methyltransferase 1 (DNMT1) expression, which in turn led to widespread DNA hypomethylation, a hallmark of aberrant gene expression in autoimmune diseases." (PMID 41376628, 2025). "An investigation of the single nucleotide polymorphisms (SNPs) of DNMT1 showed that mutations of DNMT1 are related to a variety of diseases, including cancers, heart disease, and autoimmune diseases." (PMID 37510229, 2023). "By investigating the modulation of the Treg/Th17 balance and the regulation of Foxp3 methylation through DNMT1, we hope to clarify the underlying mechanisms of TCM in autoimmune diseases and provide potential targets for therapeutic intervention." (PMID 40918088, 2025). "We furthermore provide evidence showing that local DNA methylation is correlated with DNMT1 mRNA expression which opens new venues for the treatment of autoimmune diseases such as uveitis." (PMID 30254507, 2018). "Additionally, although we suggest that a local increase of DNMT1 may be used to block cytokine expression during autoimmune disease, further extensive research is needed to investigate whether this is feasible and whether treatment can be restricted to specific genes." (PMID 30254507, 2018).
Autoimmunity (11 papers, 2015 to 2025). The occurrence of an immune reaction against the organism's own cells or tissues. "In addition, impaired DNMT1 function has a causal role in global DNA hypomethylation and autoimmunity as demonstrated by drug-induced SLE." (PMID 26330155, 2015). "Our work not only provides a scientific foundation for JPZS as a promising SLE therapeutic but also illuminates DNMT1 as a druggable target for novel epigenetic-based interventions in autoimmunity." (PMID 40918088, 2025). "Adoptive transfer of wild type Treg prevents autoimmunity in mice with Dnmt1−/−Foxp3+ Treg." (PMID 31443448, 2019). "DNMT1 deletion in the Treg lineage leads to lethal autoimmunity." (PMID 27213032, 2015). "Indeed, mice with conditional deletion of Dnmt1 in their Treg population develop autoimmunity and subsequently dies by 3 to 4 weeks earlier due to increased inflammatory genes expression, widespread mononuclear cell tissue infiltration, and exuberant T and B cell responses." (PMID 31443448, 2019). "This, in turn, has been shown to inhibit and/or decrease the DNA methyltransferase 1 (DNMT1) level, thus reducing DNA methylation in CD4+ T cells and enhancing autoimmunity." (PMID 27199979, 2016).
cholangiocarcinoma (11 papers, 2012 to 2025). A carcinoma that arises from the intrahepatic biliary tree (intrahepatic cholangiocarcinoma) or from the junction, or adjacent to the junction, of the right and left hepatic ducts (hilar cholangiocarcinoma). "In a study of cholangiocarcinoma, DNA methyltransferase 1(DNMT1) was verified as a target for miR-148a and miR-152 and the expression level of these miRNAs was decreased in cancer cells." (PMID 23683438, 2013). "In addition, SPRY4-IT1 exerted oncogenic properties via scaffolding EZH2/LSD1/DNMT1 in cholangiocarcinoma." (PMID 33029299, 2020). "In cholangiocarcinoma, miR-148a and miR-152 target DNMT1; reduced expression of these miRNAs contributes to increased DNMT1 activity, which affects transcription of the tumor suppressor genes Ras association domain family member 1 (RASSF1A) and cyclin-dependent kinase inhibitor 2A (p16INK4a)." (PMID 29401683, 2018). "Similarly, DNMT1 is targeted by miR-148a and miR-152 in cholangiocarcinoma cells, and their ectopic expression suppresses DNMT1 and induces expression of the tumor suppressor genes Ras association domain family 1A (RASSF1A) and p16." (PMID 24348513, 2013). "Braconi and colleagues verified that DNMT1 expression was elevated in some cholangiocarcinoma cell lines compared to nonmalignant human cholangiocyte lineage, and that increased was an indirect consequence of interleukin-6 (IL-6) over-expression." (PMID 21860617, 2012).